MTOR (mechanistic target of rapamycin kinase)
Diseases named in the same sentence as MTOR in open-access papers (continued):
Sharing a sentence is not in itself a finding about the gene and the disease.
renal angiomyolipomas (46 papers, 2009 to 2026). "Medical treatment revolves mainly around mTOR inhibitors, these are primarily used in hereditary renal angiomyolipomas associated with TSC or pulmonary lymphangioleiomyomatosis, which make them out of the question for this patient." (PMID 39191158, 2024). "Both everolimus and sirolimus are mTOR inhibitors employed as the primary modality for the management of TSC-associated renal angiomyolipomas (AMLs) and subependymal ependymal giant cell astrocytomas (SEGAs) in the CNS." (PMID 35652051, 2022). "Renal angiomyolipomas associated with TSC or sporadic LAM (sLAM) exhibit upregulated activity of mammalian target of rapamycin (mTOR) resulting from mutations in either TSC1 or TSC2 genes." (PMID 28792952, 2017). "In this case, the patient was initiated on sirolimus, an mTOR inhibitor that is considered the standard of care for patients with advanced disease: those with impaired lung function, lymphatic involvement, or renal angiomyolipomas." (PMID 40761985, 2025). "The choice of mTOR inhibitor used was largely determined by treatment indication: patients with active lung disease were prescribed sirolimus and patients with renal angiomyolipoma requiring treatment were generally treated with Everolimus." (PMID 38532450, 2024). "Of the 46 patients with TSC prescribed an mTOR inhibitor, 16 (21%) were prescribed Everolimus, all but one of these for renal angiomyolipoma, with one patient taking the drug for combined renal and lung disease." (PMID 38532450, 2024). "Patients with TSC2 variants exhibit more severe renal phenotypes, especially those associated with renal angiomyolipomas (AML), and they often require nephrectomy/partial nephrectomy or mTOR medication." (PMID 35870981, 2022). "The major reason for receiving systemic mTOR inhibitor in patients with facial angiofibroma was renal angiomyolipoma." (PMID 36104799, 2022). "Three children received mTOR inhibitors due to large (>3 cm) renal angiomyolipomas (rapamycin in 2 and everolimus in 1), and one child was treated with everolimus due to the presence of non-operative SEGA tumors." (PMID 34912759, 2021). "In LAM patients, there are improvements of FEV1 and FVC after the application of mTOR inhibitors and over a half achieved the shrinkage of renal angiomyolipoma." (PMID 30107845, 2018). "The aim of this study was to evaluate potential changes in the relative tissue composition of renal angiomyolipomas following the initiation of mTOR inhibitor therapy based on MRI measurements." (PMID 29232371, 2017). "It is known that systemic mTOR inhibitors have a potent effect on the vascularity of other TSC lesions such as renal angiomyolipomas." (PMID 29270462, 2017). "In this cohort, renal angiomyolipomas were most commonly treated with embolization followed by mTOR inhibitors." (PMID 28057044, 2017). "The mTOR inhibitor everolimus is indicated for the treatment of adult TSC patients with renal angiomyolipomas (AMLs) and for subependymal giant astrocytoma (SEGA) in both adults and children, based on data from the EXIST-1 and EXIST-2 trials." (PMID 28202028, 2017). "Consensus guidelines now include mTOR inhibitors as recommended treatment for asymptomatic, growing SEGAs and renal angiomyolipomas." (PMID 27351628, 2016). "Altogether, these data suggest that Akt/tuberin/mTOR pathway plays a role in the regulation of fibrosis in kidney angiomyolipomas of TSC patients." (PMID 25149531, 2014). "We completed a phase 2 multicenter trial to evaluate the efficacy and tolerability of the mTOR inhibitor, sirolimus, for the treatment of kidney angiomyolipomas." (PMID 21915260, 2011). "Hence, mTOR inhibitors represented by rapamycin and everolimus can directly inhibit mTOR activity and stop the growth or reduce the volume of renal angiomyolipoma." (PMID 34127034, 2021).
renal angiomyolipomas (continued). "Bissler JJ and colleagues demonstrated everolimus, a mammalian target of rapamycin (mTOR) inhibitor, could significant reduction in renal angiomyolipoma volume compared with placebo in Western populations." (PMID 29587809, 2018). "Fatty transformation of renal angiomyolipoma on MRI could represent a novel early indicator to identify TSC patients which respond to mTOR therapy." (PMID 29232371, 2017). "In 2008 and 2011, Bissler and McCormack demonstrated that the use of sirolimus, a mammalian target of rapamycin (mTOR) inhibitors, stabilizes LAM patients by improving lung function and exercise tolerance and decreasing renal angiomyolipoma volume." (PMID 38956624, 2024). "In recent years, systemic mTOR inhibitors have been used to treat the complications of TSC and it has been shown that they shrink TSC lesions such as renal angiomyolipomas and subependymal giant cell astrocytomas and that they improve facial angiofibromas." (PMID 29270462, 2017). "Ultimately it will be important to demonstrate that mTOR inhibitors can improve longer term outcomes in TSC and/or LAM patients with problematic kidney angiomyolipomas." (PMID 21915260, 2011). "Of the 76 patients with renal angiomyolipomas, hemorrhage was reported in three patients at baseline, who were not taking mTOR inhibitors (patients aged 31, 34, and 43 years)." (PMID 33041968, 2020). "Because the severity of kidney angiomyolipomas and other manifestations of TSC are variable, randomized trials that include patient reported or quality of life outcomes will have the highest impact regarding guiding the optimal use of mTOR inhibitors for the treatment of TSC." (PMID 21915260, 2011).
pancreatic ductal adenocarcinoma (45 papers, 2013 to 2026). An infiltrating adenocarcinoma that arises from the epithelial cells of the pancreas. "Overactivation of Pi3K/AKT/mTOR has been observed in cancer-associated fibroblasts (CAFs) isolated from the exocrine counterpart of pancreatic tumor; namely, human pancreatic ductal carcinoma (PDC)." (PMID 35884539, 2022). "Another study reported that HDAC/mTOR inhibitors synergized with a HER2 inhibitor to kill pancreatic ductal adenocarcinoma." (PMID 38475728, 2024). "PC4 accelerates the development of pancreatic ductal adenocarcinoma by activating the mTOR/p70s6k signaling pathway." (PMID 40636922, 2023). "In preclinical studies, CDK4/6 inhibitor, palbociclib, had an additive effect on cell death in pancreatic ductal carcinoma cell lines when combined with MEK or PI3K/mTOR inhibitors." (PMID 33806615, 2021). "Research carried out of animal models have demonstrated that agents targeting mTOR pathway can lead to significant inhibition of proliferation, differentiation, and tumor progression in specific pancreatic ductal adenocarcinoma subpopulations." (PMID 29214525, 2017). "Upregulation of mammalian target of rapamycin (mTOR)–4E-BP-1 signaling has been shown to be highly activated in primary human TAFs isolated from pancreatic ductal adenocarcinoma." (PMID 27515302, 2016). "In a mouse xenograft model of pancreatic ductal adenocarcinoma, concomitant inhibition of macropinocytosis/autophagy and mTOR activity resulted in antitumor effects." (PMID 26575954, 2015). "PTEN loss leads to acceleration of KrasG12D-driven pancreatic ductal adenocarcinoma (PDAC) in mice and these tumours have high levels of mammalian target of rapamycin (mTOR) signalling." (PMID 24717934, 2014). "The K-Ras isoform of Ras is mutated in over 90% of pancreatic ductal adenocarcinomas (PDAC) and there is growing evidence linking aberrant PI3K/AKT/mTOR pathway activity to PDAC." (PMID 25566081, 2014). "The mTOR pathway is aberrantly stimulated in many cancer cells, including pancreatic ductal adenocarcinoma (PDAC), and thus it is a potential target for therapy." (PMID 23437362, 2013). "Another most abundant serine/threonine phosphatases, PP2A, has been reported to show a promising utility, for example, combining PP2A activation with mTOR inhibition reduces c-Myc expression, thereby inhibiting proliferative signaling and inducing cell death in pancreatic ductal adenocarcinoma." (PMID 40263288, 2025). "In addition, the HGF-MET axis regulates mTOR activity and controls serum starvation-mediated autophagy and biogenesis In pancreatic ductal adenocarcinoma, several studies have reported that MET promotes malignant phenotypes and contributes to tumor growth." (PMID 34956177, 2021). "Notably, our further experiments showed that TEOA induced ACD in pancreatic ductal adenocarcinoma (PDAC) cells by inactivating the mTOR/p70S6k/S6 signaling pathway." (PMID 34692691, 2021). "Notably, our further experiments showed that TEOA induced autophagic cell death in pancreatic ductal adenocarcinoma cells by inactivating the ROS-dependent mTOR/p70S6k signaling pathway." (PMID 34692691, 2021). "HnRNPA2B1 could act as a novel regulator of oncogenic K-ras, modulating PI3K/AKT/mTOR signal pathway in K-ras-dependent pancreatic ductal adenocarcinoma cells." (PMID 26805816, 2016). "However, the roles of SLC41A1 in HCC was opposite to those in human pancreatic ductal adenocarcinoma, where SLC41A1 was downregulated and inhibited proliferation, migration and invasion through magnesium-dependent Akt/mTOR inhibition and bax-regulated apoptosis." (PMID 39628683, 2024).
pancreatic ductal adenocarcinoma (continued). "Consistent with this, in pancreatic ductal adenocarcinoma (PDA), but not in non-transformed human pancreatic ductal epithelial cells, the MiT-TFE factors have been shown to escape cytoplasmic retention mediated by mTOR regulation under fully fed conditions." (PMID 32881934, 2020).
steatosis (44 papers, 2011 to 2025). Increased lipid within the cytoplasm of cells. "Within the hepatocyte, the accumulation of fatty acids leads to the production of lipid-synthesis intermediates, which causes steatosis through the mTOR pathway deregulation." (PMID 32070029, 2020). "HNF1α-mutated HCA (H-HCA) are characterized by a marked steatosis and show activation of glycolysis, lipogenesis, translational machinery and mTOR pathway." (PMID 21975049, 2011). "BCAA dysregulation activates the mammalian target of rapamycin (mTOR) pathway, exacerbating IR and hepatocyte steatosis." (PMID 40771314, 2025). "Sch B activates autophagy through the AMPK/mTOR pathway, inhibits steatosis, and promotes fatty acid oxidation, thereby alleviating the progression of NAFLD." (PMID 39175576, 2024). "Oxidative stress/damage, mTOR activation, and/or TNFα levels induced by steatosis or aging in liver triggers necroptosis in liver cells." (PMID 39514172, 2024). "Rapamycin is an immunosuppressant that can reduce steatosis by inhibiting mammalian target of rapamycin (mTOR)." (PMID 36233107, 2022). "Overall, our findings suggest that D-mannose exhibits its anti-steatosis effect in ALD by regulating hepatocyte lipid metabolism via PI3K/Akt/mTOR signaling pathway." (PMID 35464439, 2022). "It has been recently demonstrated that unsaturated fatty acids trigger steatosis by down-regulating PTEN expression in this model of hepatocytes via activation of a mammalian target of rapamycin (mTOR)/nuclear factor kappa B (NF-κB) complex." (PMID 34072137, 2021). "Our examination of neonatal Otulin∆hep livers revealed an unexpected phenotype of steatosis and aberrant mTOR signalling." (PMID 32231246, 2020). "In contrast, alcohol binging promotes autophagy as a protective mechanism of hepatocytes from direct alcohol toxicity and steatosis, probably through a reactive oxygen species (ROS)-dependent inhibition of mTOR activity." (PMID 32070029, 2020). "STAM mice treated with INK-128 presented abrogated mTOR expression and tumour progression under hypoxic conditions with lower triglycerides and steatosis." (PMID 31796646, 2019). "Altogether, our study provides the evidence, for the first time, that SCD1 expression is dispensable for AKT/mTOR-dependent hepatic steatosis and AKT/Ras-induced hepatocarcinogenesis in mice." (PMID 24069385, 2013). "All these results indicate mTOR is an important modulator for steatosis in Wnt+ mice." (PMID 38152126, 2023). "From all data, we inferred that the LKB1/AMPK/mTOR axis may be a key target for decreasing SREBP1c and ameliorating intrahepatic lipid accumulation and steatosis in obese rats." (PMID 36838721, 2023). "Indeed, irbesartan was reported to relieve steatosis in db/db mice by activating the AMPK/Akt/mTOR pathway and inducing autophagy, and the results was also a proof that irbesartan regulated autophagy in ameliorating lipid accumulation." (PMID 31191364, 2019). "Proteomics revealed reduced AKT/mTOR signaling in fibroblasts derived from steatosis patients and further establishes that the insulin-resistant phenotype is present not only in insulin-metabolizing central organs, e.g., the liver, but is also manifested in skin fibroblasts." (PMID 22969728, 2012). "Its reported biological function has been as an inducer of autophagy and steatosis in an oncogenic context, potentially through interaction with ATG family proteins and inhibition of the AKT/mTOR pathway." (PMID 39277575, 2024). "MG inhibits mTOR and activates the Nrf2-ARE pathway, enhancing autophagic flux and ameliorating hepatocyte steatosis." (PMID 39175576, 2024). "In HepG2 cells with steatosis, PGAM5 knockdown reduced insulin sensitivity, increased mTOR phosphorylation and reduced the expression of NRF2, catalase (CAT), HO-1 and GPX6." (PMID 37605246, 2023). "The ribosomal protein PRAS40, abundant in steatosis patients has been identified as a crucial regulator of insulin signaling and also as mediator of AKT signals to mTOR." (PMID 22969728, 2012).
steatosis (continued). "To understand how cyanotoxins modulate cell steatosis in HCC cells we analyzed the effect of cyanotoxins on AKT/mTOR and cellular autophagy pathways since the activation of AKT/mTOR inhibits autophagy and inhibition of autophagy increases cell steatosis in NAFLD." (PMID 37505679, 2023). "Moreover, thioredoxin interacting protein (TXNIP/VDUP1) mediates the activation of AMPK, inhibition of mTOR, and nuclear translocation of TFEB which ultimately resulted MCD diet-induced steatosis, inflammation, and fibrosis." (PMID 34711912, 2021). "Low concentrations (2.5, 5, and 7.5 μM) of ATR treatment could activate autophagy to accelerate the degradation of TGs in steatosis HepG2 cells; the mechanism may be related to the activation of the AMPK/mTOR pathway induced by the increased ADP/ATP ratio." (PMID 33101031, 2020). "Coincident with an alleviation of hepatic steatosis, we computationally detected the downregulation of IL-6/JAK/STAT3 signaling and the inflammatory response (e.g., Tlr8, Mlkl), together with impaired EMT (Lgals1) in the liver, while the expression of genes related to mTOR was enhanced by LY." (PMID 35737463, 2022). "Consequently, there was hope that inhibition of mTOR with rapalogs such as rapamycin could reduce steatosis, notably by restoring autophagy." (PMID 34711912, 2021).
vascular malformation (43 papers, 2018 to 2025). A non-neoplastic disorder that is the result of defects of vascular morphogenesis. "The PI3K/AKT/mTOR pathway is primarily associated with the slow-flow vascular malformations, namely lymphatic and venous malformations." (PMID 41157225, 2025). "Dysregulation of the mTOR pathway has been implicated in various pathological conditions, including cancer and vascular malformations." (PMID 38201347, 2023). "The dysregulation of the mTOR pathway is believed to be one of the probable causes for the formation of vascular malformations, as its products are directly involved in vascular development." (PMID 38201347, 2023). "Slow-flow vascular malformations frequently harbor activating mutations in the PI3K/AKT/mTOR cascade." (PMID 37937645, 2023). "Somatic activating gene mutations in the PIK3CA/AKT/mTOR signaling pathway result in various vascular malformations and heterogeneous clinical manifestations associated with tissue overgrowth." (PMID 34980271, 2022). "It is interesting that the majority of the identified genetic mutations causing congenital or sporadic vascular malformations activate directly or indirectly either the RAS/MAPK or the PI3K/AKT/mTOR pathways." (PMID 33078209, 2021). "Most vascular malformations inducing mutations identified so far result in the direct or indirect activation of the PI3K/AKT/mTOR or RAS/MAPK/ERK pathways." (PMID 33078209, 2021). "For instance, rapamycin is currently being investigated for the treatment of various vascular malformations associated with hyperactivation of the phosphoinositide 3–kinase/Akt/mammalian target of rapamycin (PI3K/Akt/mTOR) pathway." (PMID 33105631, 2020). "Gα is upstream of both the Ras-MAPK and the PI3K-Akt-mTOR, and previous studies of low-flow, lymphatic/venous, vascular malformations implicated the PI3K-Akt-mTOR pathway as the primary driver of these lesions." (PMID 31069062, 2019). "Most of the frequently found somatic mutations in low-flow vascular malformations occur in genes involved in the mammalian target of rapamycin (mTOR) pathway; for example, PIK3CA and TEK/TIE-2 mutations lead to a gain of function and increased activity of mTOR." (PMID 37153086, 2023). "In recent years, given the finding that somatic/germ cell mutations of RAS/MAPK/ERK and PI3K/protein kinase B/mTOR pathways might be involved in vascular malformation, mTOR inhibitor sirolimus was used in patients with LMs." (PMID 35379268, 2022). "The dysregulation of pathways associated with angiogenesis and normal vascular development, namely the phosphatidylinositol 3-kinase (PI3K)/AKT and mechanistic target of rapamycin (mTOR) pathways, have been implicated in the pathogenesis of vascular malformations." (PMID 34409065, 2021). "A good example is rapamycin, currently being tested for treatment of various vascular malformations associated with hyperactivation of the phosphoinositide 3–kinase/Akt/mammalian target of rapamycin (PI3K/Akt/mTOR) pathway and linked to mutations in PIK3CA or PTEN." (PMID 33105631, 2020). "Given its critical role, this review focuses on the PI3K/AKT/mTOR axis in vascular malformations, examining its mechanisms and highlighting potential targeted therapies for complex or refractory cases." (PMID 41430313, 2025). "This review summarizes current mechanistic insights into PI3K/AKT/mTOR signaling in vascular malformations and examines the therapeutic potential of targeted inhibitors." (PMID 41430313, 2025). "This causative association is plausible, since aberrant RAS/RAF/Erk- and PI3K/Akt/mTOR-signalling has been well characterized as the driving pathomechanism behind the formation of syndromic vascular malformations as well as malign transformation." (PMID 40632343, 2025). "Recent advances in molecular genetics have identified key mutations and signaling pathway aberrations, particularly in the PI3K/AKT/mTOR axis, as critical contributors to the etiology of vascular malformations." (PMID 41430313, 2025).